FAM223B (family with sequence similarity 223 member B)
Synonyms: CXorf52B; LINC00204B; CXorf52; NCRNA00204B
Gene: Long non-coding RNA gene on chromosome X (154,632,470 to 154,633,182, reverse strand). Ensembl gene ENSG00000272681.
Homologues: Paralogues in human: FAM223A (100% identical).